IL2 (interleukin 2)
Diseases named in the same sentence as IL2 in open-access papers (continued):
Sharing a sentence is not in itself a finding about the gene and the disease.
melanoma (continued). "Melanoma is a highly immunogenic cancer, which led to high-dose interleukin-2 (IL-2) being the first immune therapy used for stage 4 melanoma patients." (PMID 40507830, 2025). "In another study, researchers tested a combination of peptide vaccines, GM-CSF, and low-dose IL-2 in patients with melanoma at stages II, III, or IV who had undergone resection." (PMID 40746887, 2025). "Melanoma patients showed sustained IL-2 and TNF-α increases, while NSCLC patients displayed heterogeneous cytokine dynamics." (PMID 41020868, 2025). "A single-arm, multicenter phase I dose escalation trial 91 enrolled 20 patients with sarcomas, melanomas, and ovarian cancers to evaluate the safety of an OAV (TILT-123), which encoded TNF-α and IL-2 in combination with TIL therapy." (PMID 40821119, 2025). "In a retrospective report of 43 patients with LMD from melanoma treated with IT interleukin-2 (IL-2), mOS was 7.8 months but was accompanied by a high rate of symptomatic intracranial hypertension." (PMID 40100294, 2025). "In a preclinical murine setting, combining an adenovirus encoding IL-2 and TNF with TILs showed increased antitumor efficacy in comparison to single-agent treatment with virus therapy or TIL therapy in melanoma." (PMID 40107242, 2025). "One promising treatment modality for dogs with metastatic OSA or melanoma is inhaled recombinant cytokine therapy using human interleukin-2 (IL-2) or interleukin-15 (rhIL-15)." (PMID 41041167, 2025). "A preliminary trial involving individuals with advanced melanoma showed that combining a liposomal melanoma vaccine with liposomal IL-2 produced notable outcomes." (PMID 40143046, 2025). "Talimogene laherparepvec (T-VEC) and interleukin-2 (IL-2) are both used in the intralesional treatment of melanoma skin metastases." (PMID 40171522, 2025). "To evaluate the therapeutic potential of receptor‐biased PEGylated IL‐2 variants, we established a syngeneic B16F10 melanoma model by subcutaneously inoculating 1 × 10^5 tumor cells into the right flank of female C57BL/6 mice." (PMID 40108893, 2025). "Our results demonstrate that nNOS inhibitor treatment prevented T cells from melanoma-induced immunosuppression, as indicated by significant increases in IL-2+ cells in the CD3+ and CD4+ T cell populations." (PMID 40574005, 2025). "As such, IL-2 positivity was utilized as a marker for T cell activation in the human melanoma and T-cell co-culture studies." (PMID 40574005, 2025). "Phase 3 clinical trial showed that the median survival time of patients with advanced melanoma who received high doses of intravenous IL-2 reached 25.8 months compared with 18.9 months recorded in the ipilimumab group." (PMID 40469178, 2025). "The most widely studied therapy involves activating in vivo γδ T cells with zoledronate and/or IL-2, showing positive results in various cancers, including prostate, breast, and melanoma, with Vδ2 T cells expanding at tumor sites." (PMID 40148988, 2025). "Then, these cells were co-cultured with various human melanoma cell lines and measured IFNγ, TNFα and IL-2 secretion." (PMID 40181966, 2025). "In melanoma, the combination of recombinant human IL-2 and ipilimumab has demonstrated superior efficacy compared to ipilimumab alone, without increasing adverse reactions." (PMID 40469295, 2025). "IL-2 was the first factor to receive clinical approval for tumor therapy, and high-dose IL-2 is approved for treating advanced renal cell carcinoma and melanoma." (PMID 40821119, 2025). "Interleukin-2 (IL-2, Proleukin®) is one of the first immunotherapies used to treat metastatic renal cell carcinoma and melanoma." (PMID 40361381, 2025). "The IL2-sEVs promoted CD8+ T cell-mediated cytotoxicity in a melanoma model and effectively inhibited tumor growth and metastasis by a 4-fold reduction compared to the untreated control group." (PMID 40872479, 2025).
melanoma (continued). "Historically, immunotherapies such as interferon, high-dose IL-2 therapy, and dendritic cell therapy have been attempted in the treatment of melanoma." (PMID 40647561, 2025). "The adoptive transfer of ex vivo-expanded, IL-2-activated, tumor-infiltrating T cells resulted in an objective response in 50% of treated melanoma patients." (PMID 41463150, 2025). "Changes in human T cell activation through interleukin-2 (IL-2) production were investigated using an ex vivo co-culture system with human melanoma cells." (PMID 40574005, 2025). "This suggests that T cell therapy can still offer therapeutic benefits in patients with advanced melanoma who have undergone multiple lines of prior therapy, including IL-2." (PMID 39857682, 2025). "It carries three important immunostimulatory transgenes—CD40L, 4-1BBL, and IL-2—that activate DCs and enhance immune responses against melanoma." (PMID 40636453, 2025). "IL-2 was the first Food and Drug Administration-approved immunotherapeutic for metastatic renal cell carcinoma and malignant melanoma." (PMID 40789741, 2025). "IL‐2: IL‐2 secretion promotes T‐cell proliferation and tumour regression in preclinical melanoma models, but clinical trials revealed toxicity without efficacy improvement." (PMID 41292193, 2025). "In contrast, melanoma patients show more pronounced and sustained IL-2 increases, with several individuals (e.g., patient 2MM) reaching levels exceeding 300 pg/mL by six months." (PMID 41020868, 2025). "Melanoma is an immunogenic tumor in which immunomodulatory treatments with therapeutic cytokines such as IL2 and IFN alfa 2 have shown benefit." (PMID 39895413, 2025). "High immunogenicity of melanoma and spontaneous remissions encouraged clinical trials in melanoma patients with immunostimulatory regimens such as interleukin-2 (IL-2)." (PMID 41463150, 2025). "Comparable outcomes were observed in another study, in which combining anti-CD137 with an engineered IL-2-Fc fusion protein attached to PEGylated liposomes demonstrated significant antitumor effectiveness in a B16F10 melanoma model." (PMID 40143046, 2025). "TIL therapy for melanoma generally involves excising a portion of the melanoma tumor, expanding TILs that show the tumor killing response in vitro with IL-2 and other growth factors, and intravenously infusing the TILs back into the patient." (PMID 40564107, 2025). "In a study, combining gene electrotransfer of IL-2 and IL-12 at the tumor site significantly slowed tumor growth and led to complete regression in 71% of cases in a murine B16.F10 melanoma model." (PMID 40636453, 2025). "IL-2 was the pioneering cytokine granted authorization for the management of metastatic renal cell carcinoma and advanced melanoma." (PMID 40143046, 2025). "High-dose IL-2 therapy was initially used to treat cancers such as renal cell carcinoma or melanoma, given that, when administered in high doses, IL-2 promotes the expansion and survival of Teffs." (PMID 40671830, 2025). "In recent years, several combinations of anti-PD-1 and other therapies are being studied for melanoma, including combinations with interleukin-2 conjugates, oncolytic viral therapy, anti-lymphocyte activation gene (LAG)-3 antibodies, and IDO1 inhibitors." (PMID 40574005, 2025). "Overall, recent studies reflect a spectrum of outcomes for IL-2–based therapies in melanoma treatment." (PMID 40636453, 2025). "While immunotherapy use in melanoma dates back to 1984 with IL-2, effects were mixed and toxicity was significant." (PMID 41179680, 2025). "In a separate analysis of 270 melanoma patients treated with IL-2 therapy, the overall objective response rate (ORR) was 16%, consisting of a 6% complete response rate and a 10% partial response rate." (PMID 40647561, 2025). "Recent studies are starting to reveal how IL-2 and its family members impact melanoma progression and treatment response." (PMID 40636453, 2025).
melanoma (continued). "Higher plasma levels of IL-2 and IL-4 have been found to significantly correlate with reduced pigmentation in melanoma patients, especially those with acral melanoma." (PMID 40636453, 2025). "To assess the impact of Siglec-7-based CSR on T cell function, we first co-cultured engineered T cells with various human melanoma cell lines and measured TNFα, IFNγ and IL-2 secretion." (PMID 40433387, 2025). "Multiple studies on different cancer types, including melanoma, reported that the IL-2-based treatments, in some scenarios, lead to a complete or partial response." (PMID 40460357, 2025). "To further validate the specific role of CCNB1 in driving NK cell dysfunction in melanoma, we used NK-92MI cells, an IL-2-independent NK cell line widely used in studies on NK cell therapy and immune tolerance." (PMID 40430484, 2025). "This review explores the involvement of the interleukin-2 (IL-2) cytokine family in both the development and therapeutic approaches for melanoma." (PMID 40636453, 2025). "Further to envisage the putative clinical applications of orthogonal IL-2/IL-2R pairs, the efficacy of tumor-specific orthoIL-2Rβ T cells in the B16-F10 mouse model of melanoma was determined." (PMID 39114660, 2024). "They determined that the overall objective response rate for malignant melanoma was 16%, with 6% of patients achieving complete responses and 10% reaching partial responses following high-dose IL-2 treatment." (PMID 39682188, 2024). "High-dose IL-2 treatment for malignant melanoma faces similar obstacles to interferon alfa-2b limiting its use." (PMID 39682188, 2024). "Cytokine therapy has been significant, with interferon-alpha (IFNα) approved for adjuvant therapy in high-risk melanoma and certain refractory cancers, and high-dose interleukin-2 (HDIL-2) approved for metastatic renal cell carcinoma and melanoma." (PMID 39335671, 2024). "presented a case report of a male patient with nivolumab-refractory unresectable melanoma who received intralesional injections of interleukin-2 (IL-2)." (PMID 39234260, 2024). "High-dose interleukin-2 (IL-2) therapy has achieved long-term remission in a small percentage of patients with advanced melanoma and renal cell carcinoma." (PMID 38360737, 2024). "Another potential application of IL-2 therapy that has emerged recently is employing IL-2 as a neoadjuvant to treat malignant melanoma in combination with immune checkpoint inhibitor therapies such as anti-CTLA4 and anti-PD1." (PMID 39682188, 2024). "IL-2 is currently approved for the treatment of human patients with melanoma and renal cell carcinoma and is considered an important interleukin associated with immune system activation." (PMID 39728976, 2024). "A single phase II cohort investigated the prognostic role of eosinophils in 41 patients with advanced melanoma treated with a combination therapy of BEMPEG (a PEGylated interleukin-2 [IL-2] prodrug) and nivolumab." (PMID 38756652, 2024). "Recently, a fusion protein of IL-2 and pHLIP (IL2-pHLIP) demonstrated tumor targeting and resulted in effective reduction of breast and melanoma tumors in animal tumor models." (PMID 38545547, 2024). "Among the array of treatments, interferons (IFNs) and high-dose IL-2 have traditionally been at the forefront of melanoma immunotherapy." (PMID 38835341, 2024). "In a mouse melanoma model, intratumoral injection of IL-2 results in decreased tumor growth and long-term tumor dormancy depending on the presence of T cells or natural killer cells." (PMID 38419052, 2024). "Other first-line treatments included high-dose IL-2 (patient 1), interferon (patient 2), imatinib (patients 6 and 7), and a melanoma vaccine as part of a clinical trial (patient 8)." (PMID 39166179, 2024). "Recombinant IL-2, Proleukin, was approved for clinical use in 1985 for the treatment of metastatic renal carcinoma and melanoma." (PMID 39204319, 2024).
melanoma (continued). "Delivery of both agents reduced B16 melanoma tumor growth and enriched T cells and NK cells in mice, compared to NPs loaded with only IL-2." (PMID 39030582, 2024). "Failures and successes: Data from the mid-1980s demonstrating the effectiveness of interleukin-2 (IL-2) in treating patients with kidney cancer or melanoma are a noteworthy example of success." (PMID 39338894, 2024). "The upregulated expression of IL-2 in BM-MSCs slowed tumour progression in B16 melanoma-bearing mouse models." (PMID 39416732, 2024). "One of the earliest and most well-known applications of cytokine therapy is IL-2, which has been used to stimulate the proliferation and activation of T cells, particularly in the treatment of metastatic renal cell carcinoma and melanoma." (PMID 39335671, 2024). "Its effect on CD8+ T and melanoma cells was mediated by several IL2-sEV-resident miRNAs, whose expressions were upregulated by the autocrine effects of IL2." (PMID 39040109, 2024). "“Cohort D” includes patients with LMD from melanoma who will undergo treatment with IT T cells and IL-2 with primary objective of evaluating safety of this treatment." (PMID 39612029, 2024). "IL2-sEVs increased the anti-cancer ability of CD8+ T cells without affecting Treg and down-regulated cellular and exosomal PD-L1 expression in melanoma cells, causing their increased sensitivity to CD8+ T cell-mediated cytotoxicity." (PMID 39040109, 2024). "Previously, chemotherapy and high doses of interleukin-2 were available treatments for melanoma; however, they offered limited survival benefits and were associated with severe toxicities." (PMID 38410760, 2024). "IL2 is used for advanced metastatic renal cell cancer and melanoma; IFNα is indicated for hairy cell leukemia, follicular non-Hodgkins’s lymphoma, melanoma, and AIDS-related Kaposi’s sarcoma." (PMID 38534922, 2024). "The response rate in our study is identical to the ORR of 22% (2/9 patients) in a phase II study of 12 patients with advanced melanoma who received TIL-ACT with a low-dose IL-2 regimen (125 000 IU/kg over 12 days)." (PMID 39801681, 2024). "A mutant IL-2 (F42K) that binds to IL-2Rβγ with the lower affinity promoted NK cell activation but still induces the expansion of Treg cells in a mouse melanoma model." (PMID 38698855, 2024). "Tumour necrosis factor-alpha (TNFα), interleukin-2 (IL-2), and interferon-gamma (IFNγ) are shown to be critical in fighting melanoma cells." (PMID 38334660, 2024). "Various miRNAs found in exosomes derived from CD4+ T cells enhanced CD8+ T cell mediated antitumor responses in melanoma under IL-2 stimulation." (PMID 39724442, 2024). "Studies demonstrated that exosomes derived from engineered Jurkat T cells that expressed IL-2 on the surface downregulated PD-L1 levels in melanoma cells by reprogramming miRNA levels and suppressed tumour development in melanoma-bearing immunocompetent mice." (PMID 38302430, 2024). "CD4+ T cells co-cultured with B16F10/shDRG2 melanoma cells produced significantly higher levels of IL-2 than those co-cultured with B16F10/pLKO." (PMID 38802348, 2024). "IL2 has been used as a cancer immunotherapeutic since the 1980s, and can provide long-term responses, and even cures, in some melanoma and renal cell cancer patients." (PMID 38546220, 2024). "Studies have shown that miR-25-3p, miR-155-5p, miR-215-5p, and miR-375 in exosomes derived from CD4+ T cells induced CD8+ T cell-mediated antitumour responses in melanoma, which were enhanced under IL-2 stimulation." (PMID 38302430, 2024). "A phase III randomized trial in advanced melanoma patients demonstrated longer PFS with TIL plus HD IL-2 therapy compared to ipilimumab therapy." (PMID 39114660, 2024). "Various cytokines are approved for treatment of metastatic cancer, such as IL-2 for the treatment of melanoma and renal carcinoma." (PMID 38549611, 2024).
melanoma (continued). "With appropriate IL-2 therapy, the cure rates for these two types of cancer can reach 18% for malignant melanoma and 37% for renal cell carcinoma." (PMID 39317690, 2024). "In two independent studies, coadministration of the anti-VEGFR-2 CAR-T cells with exogenous IL-2 or TCR transduced cells significantly increased the tumor-free survival compared to anti-VEGFR-2 CAR-T cells alone in a melanoma murine model." (PMID 39086722, 2024). "Immunotherapy is also a treatment option for BRAF-mutant melanoma that includes treatments involving interleukin 2, interferons, and programmed cell death protein 1 (PD-1)." (PMID 39336897, 2024). "Metastatic melanoma is often treated with interleukin-2 (IL-2), either alone or in combination with chemotherapy or biotherapy." (PMID 39449907, 2024). "There is a variable response among patients receiving high-dose IL-2 treatment for malignant melanoma." (PMID 39682188, 2024). "Fucoidan-based IL-2 delivery microcapsules enhanced adoptive T cell therapy in a mouse melanoma model." (PMID 38698855, 2024). "This study is a phase 2 clinical trial with multiple treatment groups of patients with melanoma who will undergo combinations of treatment with chemotherapy, T cell infusion, high dose IL-2, and DCV (NCT00338377)." (PMID 39612029, 2024). "Analysis of IFNγ levels in the supernatant of IL-2-expanded effector OT-I CD8 cells (two expansions) co-cultured with B16-OVA melanoma cells showed higher levels of IFNγ by MCJ OK OT-I CD8 cells than WT OT-I cells." (PMID 38789421, 2024). "Among 27 patients treated with adoptive T-cell therapy (ACT) for stage IV melanoma after failing prior immunotherapies (i.e., anti-CTLA-4 and/or intravenous IL-2), higher predicted neoantigen and mutational loads were associated with clinical benefit." (PMID 39336897, 2024). "Recently, bempegaldesleukin (BEMPEG), a cytokine prodrug of pegylated interleukin-2, emerged as a new potential treatment for advanced melanoma when combined with the immune checkpoint inhibitor nivolumab." (PMID 39682188, 2024). "In a melanoma mouse model, EZH2 was associated with the epigenetic development of resistance against recombinant IL-2 (rIL2) and ICI." (PMID 37394580, 2023). "In a B16-F10 melanoma mouse model, treatment with high and intermediate doses of IL-2 inhibited tumor outgrowth compared to placebo, but treatment with low−dose IL-2 allowed more tumor outgrowth than the placebo." (PMID 36845705, 2023). "For example, melanoma and renal cell carcinoma have been shown to have high levels of IL-2R expression, making them more responsive to IL-2-based immunotherapy." (PMID 37516849, 2023). "Historically, before ICIs, interleukin-2 (IL-2) and interferon were used to treat renal cancer and melanoma." (PMID 36647169, 2023). "Of interest, addition of an anti-CXCR3 antibody after ACT in IL-2 NOG mice bearing the Me275 melanoma tumor, known to express CXCR3 ligands i.e. CXCL9/10/1140, with DMβ-transduced T cells significantly impaired tumor control." (PMID 37280206, 2023). "Evidence links dysregulated IL-2/IL-2R signaling to poor prognosis in various types of cancer, including melanoma, RCC, and breast cancer." (PMID 37516849, 2023). "During the early 1990s, clinical trials of high-dose IL-2 in patients with metastatic renal cell carcinoma and malignant melanoma showed that some patients with metastatic renal cell carcinoma and metastatic melanoma benefited from high-dose IL-2 treatment." (PMID 37305384, 2023). "Recombinant cytokines have been applied in clinics to treat cancers, such as IFN alpha for follicular lymphoma, hairy cell leukemia and melanoma and IL-2 for renal cell cancer and melanoma." (PMID 38006049, 2023). "Adoptive transfer of such pre-activated NK cells resulted in increased in vivo persistence, as compared to NK cells pre-treated with IL-2 alone, and in significant inhibition of melanoma-induced lung metastases." (PMID 37388731, 2023).